RNU6-103P (RNA, U6 small nuclear 103, pseudogene)
Gene: Small nuclear RNA gene on chromosome 16 (58,496,908 to 58,497,014, forward strand). Ensembl gene ENSG00000200556.
Homologues: Orthologues: chimpanzee U6 (100% identical), macaque U6 (96% identical). Paralogues in human: RNU6-11P (85% identical), RNU6-37P (85% identical), RNU6-1060P (84% identical), RNU6-116P (84% identical), RNU6-12P (84% identical), RNU6-13P (84% identical), RNU6-24P (84% identical), RNU6-32P (84% identical), RNU6-33P (84% identical), RNU6-34P (84% identical), RNU6-36P (84% identical), RNU6-48P (84% identical), and 1287 more.